IRF1 (interferon regulatory factor 1)
Diseases named in the same sentence as IRF1 in open-access papers (continued):
Sharing a sentence is not in itself a finding about the gene and the disease.
tumor (continued). "Therefore, the combination therapy with TTFields and anti-PD-1 activates STAT1 and IRF1 through ICD in tumor tissue, enhancing the CCL2/8-CCR2 axis and CXCL9/10-CXCR3 axis, which recruits CD8+ T and CD4+ T cells to infiltrate and kill tumor cells." (PMID 40098106, 2025). "It has been reported that inflammatory signals like IFN-γ, acting through IRF1, play a significant role in promoting this splicing switch, particularly at the invasive front of breast tumors, suggesting that the tumor microenvironment can modulate immune evasion through this mechanism." (PMID 40002189, 2025). "However, chronic overexpression of CDC25C upregulates PD-L1 in tumor cells through the STAT3/IRF1 pathway, and promotes the recruitment of Tregs, MDSCs and M2-like macrophages (M2) via chemokines such as CXCL10." (PMID 41019083, 2025). "Tumor bulk RNA-Seq data highlighted that the tumor expression of 5/32 genes (IRF1, IKZF1, SPI1, SH2B3, LAT) was each strongly correlated (Spearman’s ρ > 0.5) with at least one intra-tumor T/myeloid cell infiltration marker (CD4, CD8A, CD11B, CD45) in every one of the cancer types." (PMID 40428397, 2025). "We identified several tumor-related immune features that correlated with treatment outcome in our cohort, such as baseline tumor PD-L1 and IRF1 nuclear expression, which could, if validated, help guiding ultraprecision radiation therapy combination with ICB." (PMID 38519913, 2024). "In brief, through the combination therapy, the expressions of PD-L1 and IRF1 were significantly reduced in tumor tissues by CGA, and the interaction between PD-1 and PD-L1 was blocked by the antibody, thus the T cell mediated antitumor immunotherapy was promoted." (PMID 38164171, 2024). "However, information on the connection between IRF1 and the epithelial–mesenchymal transition of tumor cells remains incomplete." (PMID 38396830, 2024). "A lower Nur77 expression level was associated with distant metastasis (P = 0.012) and advanced tumor/node/metastases (TNM) stage (P = 0.017), whereas a higher IRF1 expression was associated with lymphatic metastasis (P = 0.013) and advanced TNM stage (P = 0.029) in ESCC patients." (PMID 38789431, 2024). "Treatment with CsnB reduced ESCC tumor growth, but both rapid growth and increased tumor size demonstrated that exogenous expression of IRF1 could considerably diminish the anticancer impact of CsnB in vivo." (PMID 38789431, 2024). "Given the in vitro synergistic anti-tumor function of IRF1 and IL-2, we further explore the potential immune cell types which might play a major role in the complex tumor microenvironment." (PMID 38915471, 2024). "IRF1 is a protective factor and functions as a tumor suppressor to prevent CRC progress." (PMID 39384770, 2024). "Importantly, we demonstrated that thimerosal can elevate intracellular ROS levels, thereby activating the RIPK3/IRF1/IRG1 axis to enhance tumor immunogenicity." (PMID 39349845, 2024). "Many microRNAs were found to inhibit IRF1 mRNA levels in various tumor cells." (PMID 38396830, 2024). "Nevertheless, the opposite effects of IRF1 on tumor growth have also been demonstrated." (PMID 38396830, 2024). "IRF1, responsible for immune response regulation and tumour suppression, may impact immune surveillance mechanisms, influencing ACC progression upon altered expression." (PMID 38524085, 2024).
tumor (continued). "In addition, we also determined that known downstream signaling molecules activated by interferon-gamma receptors associated with macrophages, namely STAT1, IRF1, and IRF5, were also correlated with poor OS outcomes in tumor samples." (PMID 38539537, 2024). "Conversely, immune activity-related signatures, including PRF1, GNLY, GZMA, GZMB, and interferon regulatory factor 1, play crucial roles in tumor cell recognition and tumoricidal, with connections to extended survival, and identifying responders to anti-PD-1 antibody treatment." (PMID 38956740, 2024). "The effect of IRF1 on tumorigenic ability of tumor cells was analyzed in vivo." (PMID 38915471, 2024). "There is also evidence that the antiproliferative and pro-apoptotic properties of IRF1 may be involved in the development of tumor resistance to several antitumor chemotherapeutic drugs, which are known to act more effectively on actively dividing cells." (PMID 38396830, 2024). "Moreover, scRNA-seq analyses revealed a significant increase in PROS1 expression in HCC tumor cells exhibiting positive expression of IRF1 or MICA." (PMID 38254761, 2024). "Research on interactions involving IRF1 could explain more profound mechanisms for such confusing effects of IFNγ on tumor growth." (PMID 38396830, 2024). "Numerous mechanisms of IRF1 regulation in cancer have been identified, including genetic, epigenetic, transcriptional, post-transcriptional, and post-translational mechanisms, although their significance for tumor progression remains to be explored." (PMID 38396830, 2024). "In addition to host anti-pathogen defense, IRF1 has been recognized to play important but opposing roles in the regulation of tumor progression." (PMID 37094077, 2023). "As we expected, IRF1 positive expression in tumor cells was consistent with MICA positive." (PMID 36765808, 2023). "Tumor transcript analysis using interferon regulatory factor 1 (IRF1) expression as a readout of IFNγ signaling suggested there may be a marginal disruption of this pathway." (PMID 38130991, 2023). "In addition to its role in the innate antiviral response, IRF1 also plays a role in adaptive immunity and tumor suppression." (PMID 37327222, 2023). "Meanwhile, since our previous study also showed that IRF1 recruited NK cells and CD8+T cells through CXCL10/CXCR3 axis, we investigated whether IRF1-MICA signaling recruited anti-tumor immune cells via the CXCR3 receptor." (PMID 36765808, 2023). "This suggests that IRF1, as an upstream regulator of PANoptosis, induces PANoptosis in colon cells to protect them from tumor development, and that IRF1 may therefore be a potent target for the regulation of multiple programmed cell death." (PMID 38069556, 2023). "IRF1 was highly expressed in various immune cells and tumour cells." (PMID 36519208, 2023). "As an additional test to determine whether the AN18 antibody was impacting IFNγ signaling within the tumor, we compared the ratio of IRF1:IFNγ transcripts, since IRF1 expression is in part dependent on the presence of IFNγ." (PMID 38130991, 2023). "It is noteworthy that the loss of IRF1 alleles per se does not lead to spontaneous tumor development." (PMID 37063830, 2023). "In this scenario, adding a laparotomy procedure to the minimally invasive removal of the primary tumor from the animals caused an increase in IL-6 and IL-8 levels, elevated NF-κB, reduced IRF1 activity in excised tumor transcriptomes and initiated an outbreak of micrometastases." (PMID 37296983, 2023). "Hepatic tumors inoculated with IRF-1-primed-tumor-derived EVs slowed the growth of the tumors." (PMID 38138963, 2023). "IRF1 induces PANoptosis in colon cells to protect them from tumor development." (PMID 38069556, 2023). "However, these novel findings reveal a complex role for IRF-1, which upregulates PD-L1 in the inflammatory tumor microenvironment." (PMID 36980210, 2023).
tumor (continued). "Thus, evidence further accumulates suggesting IRF1-inducing agents to be more broadly considered as adjuvants in tumor therapy." (PMID 35436994, 2022). "Moreover, the depletion of methyltransferases METTL3 and METTL14 in tumor cells is found to prominently induce the activation of the IFN-γ-STAT1-IRF1 signaling axis through the stabilization of the STAT1 and IRF1 mRNA via YTHDF2." (PMID 35693795, 2022). "Also, PSMB9 is directly regulated by anti-oncogenic IRF1, a well-known gene with suppressor tumor activity." (PMID 36291793, 2022). "Therefore, mutations and deletions of proteins associated with this pathway on tumor cells, such as JAK1 and JAK2, STAT1, IRF1, and other IFN receptor chains, can lead to drug resistance to immunocheckpoint inhibitors." (PMID 36185620, 2022). "Transcription factor (TF) activity prediction, using the DoRothEA resource, to identify potential regulons responsible for the signalling and phenotypes associated with HPS in HiFi tumours revealed a strong association with STAT1, STAT2, IFN (IRF1, IRF9) and NFκB (NFKB1, REL, RELA, RELB) TFs." (PMID 35477539, 2022). "Additionally, we recently reported the tumor suppressive function of IRF1 during CRC, as IRF1 potentiates inflammatory cell death, PANoptosis, in cancer cells." (PMID 35205671, 2022). "Furthermore, the interferon regulatory factor 1 (IRF-1), a key transcriptional regulator, was activated in tumor cells through stimulation by cytokines released from TAMs." (PMID 35267626, 2022). "In these tumor tissue, most pyroptosis-related molecules, particularly IRF1, GZMB, CASP5, BAK1 and AIM2, were consistently inhibited in the cell cycle, DNA damage response, hormone AR and RTK signaling pathway, but highly activated in the apoptosis signaling way." (PMID 36437960, 2022). "IRF1 has been identified as a tumor suppressor in breast cancer." (PMID 36460706, 2022). "Notably, CTL subset 7 specifically highly expresses IRF1 and AES, of which IRF1 has been found to be associated with tumor suppressor activity in multiple studies." (PMID 36358600, 2022). "Furthermore, retinoids also activate the transcription factor IRF1, a tumor suppressor involved in activating the tumor-selective death ligand TRAIL, leading to apoptosis through the extrinsic apoptotic pathway." (PMID 36362917, 2022). "Moreover, IRF1 expression in tumor cells was also reported to be critical for the immune response to adoptive T cell therapy, as well as macrophage infiltration and memory CD4+ T cell activation." (PMID 34277600, 2021). "In the ulcerated tumor, B cells showed increased markers associated with type-2 responses such as CCL17, IL4R, and decreases in interferon-stimulated genes (IFI44L, STAT1, IFITM1, MX1, IRF1)." (PMID 34583709, 2021). "Besides its function as a transcription factor, IRF1 has been found to increase apoptotic activity as part of its tumor suppressive roles." (PMID 34589482, 2021). "In addition to protection from infection by pathogens, IRF1 is recognized to be a key regulator of tumor progression and to have tumor suppressor properties." (PMID 33476326, 2021). "IRF1 suppresses tumor cell growth, stimulating immune responses against tumor cells." (PMID 34202278, 2021). "In addition, we also examined the ability of BCA2 to regulate NF-κB and IRF1 in transformed and non-tumor breast epithelial environments." (PMID 34589482, 2021).
tumor (continued). "The fact that BCA2 fails at inducing the anti-tumor function of IRF1 in the MDA-MB-231 ER– cell line is consistent with the aggressive nature of these tumor cells, which may have evolved mechanisms to override BCA2 actions." (PMID 34589482, 2021). "In addition to NF-κB, we also found that BCA2 activates IRF1, a well-known immunomodulatory transcription factor and tumor suppressor." (PMID 34589482, 2021). "As a relevant tissue pattern, we could detect tumor areas of “inducible” pSTAT1Y701 and IRF1 expression containing clusters of positive tumor cells and TAMs." (PMID 34220848, 2021). "In addition to immune-related functions (e.g., as antiviral gene, master regulator of acute inflammation, and main effector of IFNγ signaling), IRF1 was also characterized as a tumor-suppressor." (PMID 33668131, 2021). "Thus, IRF1 inhibition by RAS-MEK is predicted to concomitantly promote tumorigenicity, alter the interactions between tumor- and immune cells and enhance the susceptibility of cancer cells to OVs." (PMID 33668131, 2021). "In addition to NF-κB, our previous work uncovered that BCA2 also regulates IRF1, a well-known tumor suppressor." (PMID 34589482, 2021). "In fact, compared to the other cells used in this study, the MDA-MB-231 cells exhibited the highest nuclear levels of IRF1, suggesting that these cells may be trying to regain control over cell proliferation by up-regulating this tumor suppressor." (PMID 34589482, 2021). "We also investigated how IRF-1 tumour suppressor regulates HPV16 E6-induced cell proliferation." (PMID 33076322, 2020). "Collectively, all our data provide information that will improve understanding of the cellular and molecular mechanism for HPV16 E6 biological function, and importance of the IRF-1 tumour suppressor in controlling tumour growth and angiogenesis of HPV16 E6 oncoprotein in cervical tumourigenesis." (PMID 33076322, 2020). "Therefore, the role of IRF1 in the COAD immune microenvironment was further explored in the Tumor IMmune Estimation Resource (TIMER) site." (PMID 32925784, 2020). "Here, our data further support a tumour-suppressive role for IRF-1 in GC metastasis." (PMID 31186404, 2019). "Thus, IRF-1 has a tumour metastasis-suppressive role in GC by preventing MIR17HG-miR-18a/19a axis mediated Wnt/β-catenin signalling." (PMID 31186404, 2019). "In addition, IRF1 is involved in the negative regulation of Treg cells leading to the reactivation of an anti-tumor immune response." (PMID 31319484, 2019). "In recent years, the role of IRF-1 in tumour metastasis has gradually attracted attention." (PMID 31186404, 2019). "Given the anti-MIR17HG-mediated metastatic effects of IRF-1 in vitro, we subsequently questioned whether the inhibition of IRF-1 affects tumour metastasis in vivo." (PMID 31186404, 2019). "Indeed the majority of Fbxw7α substrates are oncogenic, which makes IRF1 (a putative tumour suppressor) an unusual substrate for this pathway." (PMID 30854564, 2019). "IRF-1 is a tumor suppressor and inhibits phenotypic changes." (PMID 31753025, 2019). "Interestingly, IRF-4 is an endogenous antagonist of IRF-1, which is known for its tumor suppressing activity." (PMID 29599126, 2018). "SUMOylation of IRF-1 stabilizes this protein and protects it from degradation, but also leads to loss of its transcriptional activity, inhibiting IRF-1-mediated apoptosis and tumor-suppressing activity; therefore, levels of IRF-1 SUMOylation are increased in tumor cells." (PMID 29599126, 2018). "Nevertheless, considered together with other findings, whereas IRF-2 may be classified as an oncogene, these results are consistent with IRF-1 having tumor-suppressing potential." (PMID 29599126, 2018).
tumor (continued). "Indeed, we found a strong reduction of Irf1 mRNA level in total lung cells derived from tumor bearing STAT1 KO mice compared to tumor bearing wild-type controls." (PMID 30647851, 2018). "The following section describes the different routes by which the function of IRF-1 and, thereby, its tumor-suppressing role may be lost in human cancers." (PMID 29599126, 2018). "Additionally, the drug combination upregulated PINK1, IRF1, PPP1R15A, CRABP2, SCRN1, LIMA1, and TGFBI; all genes associated with tumor suppression functions in PCa." (PMID 29545934, 2018). "In addition, a high IRF-2/IRF-1 protein ratio positively correlates with tumor invasion and metastatic ability in human HCC cell lines." (PMID 29599126, 2018). "The results may suggest that the PD1/PDL1 reverse signaling may activate the eIF2α/ATF4 pathway in tumor surrounding cells and IRF1 may be active in regulating PDL1 expression in the tumor tissue." (PMID 30305853, 2018). "Moreover, the transcription factor interferon regulatory factor (IRF)-1 was reported to manifest tumour-suppressor activity in tumour cells." (PMID 28233863, 2017). "Here the authors show that mitochondrial membrane protein Fam73b regulates TLR-mediated mitochondrial switching of fusion to fission to induce IL-12 production via accumulation of Parkin and stabilization of IRF1 in macrophages, resulting in control of anti-tumor immunity in mice." (PMID 29180626, 2017). "In addition, microarray analysis comparing colonic gene expression in IRF-1-KO mice and WT mice revealed decreased expression of caspases and tumor suppressor genes in the IRF-1-KO mice." (PMID 29267211, 2017). "The IRF1-mediated IFNγ signaling pathway regulates MHC class I antigen presentation in tumor cells." (PMID 28977839, 2017). "Further, IRF1 has been shown to play roles in regulating apoptosis and tumor suppression." (PMID 28005952, 2016). "As a tumor suppressor, IRF1 expression is decreased in a variety of human cancers." (PMID 27252695, 2016). "ASS1 and IRF1 have been reported to act as tumor-suppressors." (PMID 26036313, 2015). "DTX3L and ARTD9 act together as repressors of the tumor suppressor IRF1 in mPCa cells." (PMID 26654227, 2015). "We found that the role of iNOS was not as importantas IRF-1, since iNOS deficient mice were more susceptible to tumor growth when comparedwith WT mice, but in comparison with IRF-1 deficient mice iNOS deficient mice were lesspermissive to tumor growth." (PMID 25659093, 2015). "STAT1 has been initially considered to act exclusively as tumor suppressor and key regulator of the surveillance of developing tumors, primarily by activating growth-inhibitory and pro-apoptotic signaling in tumor cells, mainly mediated by IRF1." (PMID 26654227, 2015). "Our work is consistent with the idea that immune cells reacting to invading areas of a growing tumor generate IRF-1 in the tumor perhaps through release of IFN-γ, which eventually leads to AS to generate CEACAM1 L-isoform expression not only on T cells but in non-inflamed epithelial cells as well." (PMID 24650050, 2014). "Importantly, IRF1 knockdown in tumor cells significantly impeded migration of monocytes towards BV6-treated tumor cells." (PMID 25501823, 2014). "IRF-1 may suppress tumor proliferation by inhibiting the cell cycle, reducing susceptibility to transformation by oncogenes or inducing apoptosis, development of natural killer (NK) cells and differentiation of Th1 and CD8+ T cells." (PMID 23420765, 2013).